DGKA (diacylglycerol kinase alpha)
Diseases named in the same sentence as DGKA in open-access papers (continued):
Sharing a sentence is not in itself a finding about the gene and the disease.
colon cancer (1 paper, 2014). "Here we identify DGKα upregulation as part of the reprogramming that occurs when breast and colon cancer cells grow in a 3D microenvironment." (PMID 25339152, 2014). "We next tested the effect of DGKα inhibition on the Caco-2 cell line that, although it is classified as colon cancer, forms acinar-like structures in matrigel culture and is widely used to study colon morphogenesis." (PMID 25339152, 2014). "We analyzed the DGKα contribution to breast and colon cancer in 3D cell cultures." (PMID 25339152, 2014). "We tested whether PI3K/Akt inhibition in SW480 colon cancer cells triggered activation of Src and tyrosine signaling, and if this correlated with transcriptional upregulation of DGKα." (PMID 25339152, 2014). "We next examined the contribution of DGKα to maintain 3D growth in vivo, using DGKα silenced SW480 colon cancer cells in xenograft assay models." (PMID 25339152, 2014).
depression (1 paper, 2021). "The DMRs were located at/near 19 genes, among which DGKA and NIPA2 might play an important roles in regulating depression." (PMID 34341332, 2021).
epilepsy (1 paper, 2018). A brain disorder characterized by episodes of abnormally increased neuronal discharge resulting in transient episodes of sensory or motor neurological dysfunction, or psychic dysfunction. "We also sought to investigate a role for Dictyostelium DGKA in attenuating the effects of other potential epilepsy treatments." (PMID 30135067, 2018). "Finally, we show that VPA, lithium and novel epilepsy treatments function through DAG regulation, and the presence of DGKA is necessary for compound-specific increases in DAG levels following treatment." (PMID 30135067, 2018).
esophageal squamous cell carcinoma (1 paper, 2025). Esophageal squamous cell carcinoma (ESCC) is a type of esophageal carcinoma (EC) that can affect any part of the esophagus, but is usually located in the upper or middle third. "In esophageal squamous cell carcinoma (ESCC), stromal TAM-derived CCL22 activates the DGKα/NF-κB pathway, upregulating multiple ATP-binding cassette transporters and reducing intracellular cisplatin accumulation, thereby promoting cisplatin resistance." (PMID 41417432, 2025).
fibrosis (1 paper, 2016). the formation of excess fibrous connective tissue in an organ or tissue in a reparative or reactive process. "However, the additional induction of DGKA with ionizing radiation selectively led to synergistic growth impairment in fibroblasts from patients later developing fibrosis that were characterized by lower DGKA DMR methylation and increased DGKA inducibility." (PMID 26964756, 2016). "In summary, we found synergistic effects on cell growth and fibroblast activation after inhibition of DGKA and PRKCA in fibroblasts from patients developing fibrosis." (PMID 26964756, 2016). "We focused our investigations on a DMR at the DGKA locus that was less methylated in patients developing fibrosis compared with those that did not." (PMID 26964756, 2016).
gastric cancer (1 paper, 2020). A primary or metastatic malignant neoplasm involving the stomach. "In gastric cancer, however, DGKA expression was found to be modulated by lipid metabolism and high DGKA levels were related with good survival." (PMID 32477950, 2020).
invasive breast carcinoma (1 paper, 2014). A carcinoma that infiltrates the breast parenchyma. "In here we investigate the signaling pathway by which DGKα mediates SDF-1α-induced matrix invasion of MDA-MB-231 invasive breast carcinoma cells." (PMID 24887021, 2014).
juvenile arthritis (1 paper, 2021). "This is the first demonstration of a DGK family member suppressing macrophage function; one prior report linked DGKζ to macrophage activity in juvenile arthritis and cytokine storm mouse models, but it showed a stimulatory role for DGKζ opposite that we observed for DGKα." (PMID 34804012, 2021).
juvenile periodontitis (1 paper, 2019). "The role of DGKα in neutrophils is evidenced by its aberrant behavior in juvenile periodontitis patients, which express an inactive DGKα transcript." (PMID 31766109, 2019).
leukemia (1 paper, 2023). A malignant (clonal) hematologic disorder, involving hematopoietic stem cells and characterized by the presence of primitive or atypical myeloid or lymphoid cells in the bone marrow and the blood. "Together, we concluded that the anti-leukemia efficacy of ritanserin is due to its inhibition of DGKα, mainly through negative regulation of the Jak-Stat and MAPK signaling pathways." (PMID 37392305, 2023). "Collectively, these data indicated that high expression of DGKα in AML was related to the poor prognosis, which also suggested that the anti-leukemia effect of ritanserin is partly due to the inhibition of DGKα." (PMID 37392305, 2023). "As a pro-oncogene, DGKα promotes proliferation and anti-apoptosis in leukemia." (PMID 37392305, 2023). "Thus, we deduced that the anti-leukemia efficacy of ritanserin might be influenced by DGKα-induced Jak-Stat/MAPK pathways." (PMID 37392305, 2023).
liver cancer (1 paper, 2024). An epithelial or non-epithelial malignant neoplasm that arises from the liver. "We believe that DGKα is a promising biomarker and therapeutic target molecule for primary liver cancer, including not only HCC but also ICC." (PMID 38716625, 2024). "We have confirmed the antitumor effects of DGKα inhibitors using a mouse model of liver cancer." (PMID 38716625, 2024). "DGKα expression can evaluate cell proliferation regardless of the histological type of primary liver cancer." (PMID 38716625, 2024).
lung adenocarcinoma (1 paper, 2015). A carcinoma that arises from the lung and is characterized by the presence of malignant glandular epithelial cells. "In an exploratory analysis, the protein and mRNA expression levels of DGKa, PDE4A and PDE4D were examined in the five EGFR-mutant lung adenocarcinoma cell lines in an effort to explore whether DGKa regulates MTOR transcription through modulation of cAMP levels." (PMID 26639561, 2015).
lymph node metastasis (1 paper, 2025). "This molecular mechanism might reasonably explain the significantly higher lymph node metastasis rate in DGKα‐positive patients treated with radical cystectomy in our clinical cohort." (PMID 40013327, 2025).
oropharyngeal squamous cell carcinomas (1 paper, 2020). "In the present study, we describe a specific monoclonal antibody DaMab-8 (mouse IgG1, kappa) against DGKα, which is extremely useful for performing immunohistochemical analysis for T cells in oropharyngeal squamous cell carcinomas." (PMID 31099705, 2020).
papillary carcinoma (1 paper, 2022). A malignant epithelial neoplasm characterized by a papillary growth pattern. "The results revealed that metabolism-related pathways, such as oxidative phosphorylation and glycerophospholipid metabolism (PCYT2, MBOAT7, DGKA, etc.), were enriched in papillary carcinoma." (PMID 35659036, 2022).
Salmonella Infections (1 paper, 2021). Infections with bacteria of the genus SALMONELLA. "Two genes, IL6 and DGKA, overlapped between the potential targets in Pingwei Pill, colistin, and the known therapeutic targets for Salmonella infection." (PMID 34663394, 2021). "IL6 and DGKA were another two key targets between Pingwei Pill and colistin, the two genes were also Salmonella infection related genes, which mainly played a role of focal adherents, bacterial invasion of epithelial cells and chemokine signaling pathway." (PMID 34663394, 2021). "Taken together, our results established that Pingwei Pill is the potential candidate for Salmonella infection by targeting MCR-1, IL6 and DGKA genes to recover the colisitn activity, and inhibit the bacteria adhesion and invasion." (PMID 34663394, 2021).
Skin ulcer (1 paper, 2021). A discontinuity of the skin exhibiting complete loss of the epidermis and often portions of the dermis and even subcutaneous fat. "Given that DGKα had been shown to regulate other immune cells and that macrophages are known to play key roles in wound healing, including in the context of chronic wounds such as skin ulcers, we hypothesized that DGKα regulates macrophage activity as well." (PMID 34804012, 2021). "While DGKα has not been firmly linked to the innate arm of the immune system, we came to suspect such a connection following the observation that there were dramatically fewer skin ulcers over subcutaneous melanoma tumors in Dgka-/- versus wild-type (WT) mice." (PMID 34804012, 2021).
type 1 diabetic (1 paper, 2020). "To confirm the value of DGKα as a therapeutic target, we also sought to determine whether EGCg improved albuminuria in DN via DGKα by using the streptozotocin-induced type 1 diabetic model mice." (PMID 32678222, 2020). "Here, we investigated whether and how DGKα contributes to the amelioration of DN upon stimulation by EGCg by using streptozotocin-induced type 1 diabetic model mice." (PMID 32678222, 2020).
tumor (43 papers, 2013 to 2026). "The adoptive transfer of DGKα/DGKζ-deleted CAR-T cells caused a compelling tumor rejection in a subcutaneous xenograft model." (PMID 38022587, 2023). "In human hepatocarcinoma, it has been shown that DGKα is associated with tumor progression by activation of the mitogen-activated protein kinase (MAPK) pathway." (PMID 36358678, 2022). "The ability to limit T-cell activation in the tumor microenvironment, along with the promotion of tumor survival resulting from PA generation, are a tandem that underlie the challenges of therapeutic development in cancer, and present an opportunity for targeting DGKα in this context." (PMID 34804012, 2021). "In general, it is reported that stress conditions (as radiation therapy) enhance expression of DGKα in cells and its expression is particularly relevant in tumor‐infiltrating T cells." (PMID 40859612, 2026). "Accordingly, DGKζ inhibition synergizes with checkpoint inhibitors in restoring tumor‐infiltrating lymphocytes activity toward cancer cells, similarly to what observed with DGKα and putting also this isoform at the center of intensive research for inhibitors." (PMID 40859612, 2026). "High DGKα activity on one side propels tumor cell growth and motility and on the other side makes tumor‐infiltrating T cells unresponsive to cancer cells, facilitating the immune‐escape." (PMID 40859612, 2026). "Both DGKα and DGKζ inhibitors are known to enhance immune responses, thus achieving a dual effect: direct tumor growth suppression and stimulation of immunosurveillance." (PMID 41227366, 2025). "Expression levels of DGKα in tumor specimens from patients with BC treated with radical cystectomy were analyzed." (PMID 40013327, 2025). "DG is catalyzed into phosphatidic acid by diacylglycerol kinases (DGK); and DGK isoforms (DGKα and DGKζ) are expressed in tumor-infiltrating T lymphocytes." (PMID 38617000, 2024). "CRC stage II (pT3N0M0) patients who highly expressed DGKα in cancer cells and stromal cells that were considered equal to tumor‐infiltrating lymphocytes had a worse prognosis." (PMID 38716625, 2024). "For RFS analyzed excluding curability C, hepatitis virus infection, tumor number, pathological stage, and DGKα positivity were prognostic factors in the univariate analysis." (PMID 38716625, 2024). "The potential therapeutic value of DGK inhibitors in the treatment of tumors and hematological diseases has led our group to develop new DGKA-specific inhibitors and explore pan-cancer studies to identify potentially sensitive tumor types." (PMID 37509516, 2023). "To address the effect of inhibiting DGKα/ζ in tumor-specific T cells, we used TRP1high and TRP1low transnuclear mice, originally generated by somatic cell nuclear transfer from two different CD8 T cells recognizing TRP1 peptide presented by H2-Db." (PMID 38000024, 2023). "Consistent with the in vivo tumor growth inhibition in the adoptive transfer models, tumor growth in Dgkα or Dgkζ knockout mice was attenuated." (PMID 38022587, 2023). "Collectively, our findings highlight DGKα/ζ as therapeutic targets for augmenting tumor-specific CD8 T cell function." (PMID 38000024, 2023). "Here, we use a potent DGKα/ζ lipid kinase inhibitor to enhance tumor-specific CD8 T cell activation and effector functions." (PMID 38000024, 2023). "As an isoform of DGKα, DGKzeta is highly expressed in lymphoid tissues, which affects tumor cell apoptosis and cell cycle arrest." (PMID 38033488, 2023). "In summary, our analyses have revealed that Dgk/DGKα plays an important role in Ras-driven polarity-impaired tumour growth in both the Drosophila model and human epithelial cell lines." (PMID 36861754, 2023). "Yet, how DGKα/ζ inhibition can modulate tumor-specific T cell activity in the context of varying TCR affinities or limited antigen presentation remains underexplored." (PMID 38000024, 2023).
tumor (continued). "In hepatocellular carcinoma, it was shown that DGKα is involved in the tumor progression by activation of the MAPK pathway via modulation of Raf-1 (C-Raf)." (PMID 36358678, 2022). "Our finding of the phosphorylation-dependent adaptor function of DGKα revealed an important mechanism by which the CCR4/DGKα/FAK complex coordinately regulates CCL22-induced tumor metastasis." (PMID 35962191, 2022). "In esophageal squamous cell carcinoma, PA production by DGKα has been associated with the activation of Akt/NF-κB signaling, which, in turn, reduced cAMP levels and PTEN activity leading to tumor progression." (PMID 36358678, 2022). "Hypofunctional CD8+ tumor-infiltrating T cells from clear cell renal carcinoma also displayed upregulation of DGKα." (PMID 33946954, 2021). "In fact, overexpression of DGKα, one of ten isoforms, enhanced cancer cell proliferation and tumor growth, whereas knockdown of DGKα reduced cell viability in a range of cancer types." (PMID 33413672, 2021). "Since R59022 is a relatively selective DGKα inhibitor, restored degranulation capacity of tumor-infiltrating lymphocytes (TILs, such as CD8+ T cells and NK cells) was attributed to DGKα." (PMID 33946954, 2021). "Xenograft experiments also demonstrated that DGKα knockdown and inhibition affects tumor growth, angiogenesis, and survival of mice with intracranial and subcutaneous tumors." (PMID 32722576, 2020). "Pharmacological or genetic DGKα silencing restricted tumor growth in vivo, thus confirming the function of DGKα in malignant transformation." (PMID 32722576, 2020). "DGKA is distinctly expressed in different tumor cell types while their normal tissue counterparts are often devoid of its expression; this suggests that it is able to enhance tumor cell proliferation." (PMID 32477950, 2020). "In renal clear cell carcinoma, for example, the activity of tumor-infiltrating NK cells was inhibited by strong expression of DGKA and insufficient ERK pathway activity." (PMID 32477950, 2020). "Inhibition of DGKA or reactivation of the ERK pathway reconstituted the anti-tumor activity of T and NK cells." (PMID 32477950, 2020). "This was also observed in other tumors where inhibition of DGKA and other DGKs restored pro-apoptotic signaling in normal T and NK cells against tumor." (PMID 32477950, 2020). "Because DGKα has both pro-tumoral and anti-immunogenic properties, the DGKα-selective inhibitors would simultaneously have anti-tumoral and pro-immunogenic (anti-tumor immunogenic) effects." (PMID 27583247, 2016). "Such hyporesponsive or anergic tumor-infiltrating T cells or CAR-T cells show decreased Ras/Erk activation but elevated DGKα and ζ levels." (PMID 27891502, 2016). "Although how DGKα and ζ double deficiency differentially affects CAR-T cell mediated anti-tumor immunity and CD8 T cell mediated anti-microbial immune responses is unclear at present." (PMID 27014906, 2016). "Pharmacological or genetic DGKα silencing impaired tumor growth in vivo confirming its function in malignant transformation." (PMID 25339152, 2014). "In this latter case, our data demonstrate that DGKα expression, upregulated in response to PI3K/Akt inhibition, contributes to Src activation, and provide additional proof of DGKα as part of tumor escape mechanisms." (PMID 25339152, 2014). "Western blot analysis of tumor lysates confirmed that DGKα silencing was maintained along the experiment." (PMID 25339152, 2014). "Inhere we investigated the role of DGKα in invasive signaling of SDF-1α, one of the key signals driving metastasis, whose receptor, CXCR4, is strongly associated to tumor growth and spontaneous metastasis formation." (PMID 24887021, 2014). "We found that DGKα silencing or inhibition prevented cancer cell growth in 3D culture as well as tumor growth in vivo." (PMID 25339152, 2014).